APP (amyloid beta precursor protein)
Diseases named in the same sentence as APP in open-access papers (continued):
Sharing a sentence is not in itself a finding about the gene and the disease.
fragile X syndrome (15 papers, 2013 to 2024). A genetic syndrome caused by mutations in the FMR1 gene which is responsible for the expression of the fragile X mental retardation 1 protein. "Cleavage of APP can produce β-amyloid (Aβ), which is overexpressed in the brain of Fmr1 knockout mice, suggesting a pathogenic role in fragile X syndrome." (PMID 25767435, 2015). "APP metabolites appear to directly affect translational signaling pathways, which have been linked to single gene forms of syndromic ASD (Fragile X Syndrome, PTEN, Tuberous Sclerosis Complex)." (PMID 37799731, 2023). "In spite of the association between Fragile-X Syndrome and Amyloid Beta Precursor Protein expression, no bb-CpG with differential methylation found in AD patients was differentially methylated in Fragile-X patients." (PMID 39060467, 2024). "In fragile X syndrome, this interaction leads to increased cleavage of APP, suggesting that similar processes may be occurring in AD brain." (PMID 24886239, 2014). "We found a fascinating profile of APP metabolites in plasma from children with Fragile X Syndrome (FXS) and adult FXS brain tissue: increased levels of total APP, sAPPα, and Aβ peptide." (PMID 37799731, 2023). "Early studies found that activation of post-synaptic mGluR5 increases amyloid precursor protein (APP) and beta amyloid (Aβ) expression via release from FMRP repression, an extension of the research on Fragile X syndrome." (PMID 32939596, 2021). "The two neurodevelopmental disorders—ASD and Fragile X Syndrome (FXS) are connected with altered APP metabolism and with Aβ plaque formation, which may affect learning and memory function." (PMID 32170673, 2020). "Over recent years there has been much interest in how the Amyloid-β Precursor Protein (APP) may contribute to autism spectrum disorder (ASD) and Fragile X Syndrome (FXS), particularly to the macrocephaly often seen in these disorders." (PMID 37808474, 2023). "Fragile X syndrome (FXS), which is commonly marked by a comorbid diagnosis of ASD, involves the disruption of normal interaction between the fragile X mental retardation protein (FMRP) and metabotropic glutamate receptor (mGluR) which misregulates APP mRNA translation." (PMID 23801940, 2013).
periodontitis (15 papers, 2016 to 2025). An acute or chronic inflammatory process that affects the tissues that surround and support the teeth. "Currently, there is only one study that employed APP-transgenic (Tg) mice and the study implies that periodontitis exacerbates the hallmark pathology and symptoms of AD." (PMID 31366073, 2019). "Immunolocalisation of APP in gingival tissue was also investigated suggesting a potential mechanism by which chronic periodontitis may be biologically linked to the clinical onset or progression of AD." (PMID 38230738, 2024). "However, as AD is also characterized by the presence of neurofibrillary tangles, 3 × Tg-AD mice bearing mutations on presenilin 1, APP, and tau protein were employed in this study to investigate the impacts of periodontitis on AD." (PMID 36915108, 2023). "Compare differences of AD pathway molecules in healthy tissues and periodontitis tissues, including amyloid beta (A4) precursor protein (APP), a key gene in AD, interleukin-1 beta (IL-1β), and complement component 1 (q subcomponent, A chain) (C1QA)." (PMID 41170438, 2025). "Animal study to investigate the effect of periodontitis on learning capacity and memory of APP/presenilin (PS1) transgenic mice along with the mechanisms underlying these effects." (PMID 41170438, 2025). "Animal study to explore the influence of periodontitis-related salivary microbiota on AD based on the gut-brain crosstalk in APP/PS1 transgenic mice." (PMID 41170438, 2025). "Periodontitis induced by P. gingivalis-LPS increased the expression of APP and its homologs (APLP1 and APLP2)." (PMID 32714134, 2020). "Cognitive function was significantly impaired in periodontitis-induced APP-Tg mice, compared to that in control APP-Tg mice." (PMID 29134111, 2017). "To develop experimental periodontitis in APP-Tg mice, we inoculated the mice with P. ginigivalis ATCC 33,277 mixed with carboxymethyl cellulose, which was delivered orally." (PMID 29134111, 2017). "We proposed that continuous chronic peripheral and intrinsic inflammation, such as periodontitis and its chain reactions, could be a key feature of inflammatory pathology and attribute to abnormal APP processing and Aβ production, similar to a previous study." (PMID 33757547, 2021). "Increase of inflammatory factors, activation of microglia and astrocytes and abnormal APP processing were found, suggesting that periodontitis might be a possible contributor to AD-like pathology." (PMID 32714134, 2020). "Our study demonstrated that periodontitis induced by P. gingivalis -LPS could facilitate abnormal APP processing." (PMID 32714134, 2020). "This indicated that periodontitis induced by P. gingivalis-LPS could modulate APP processing through enhanced β- and γ-site secretase activity, consistent with the increase of APP in patients with chronic periodontitis." (PMID 32714134, 2020). "According to our results, cytoplasmic yellow/brown particles could be found and intracellular levels of Aβ1-42 as well as APP were increased in the cortex of LPS group, indicating that periodontitis could induce abnormal APP processing." (PMID 32714134, 2020). "Furthermore, cognitive function was significantly impaired in the periodontitis-induced APP-Tg mice relative to sham-infected APP-Tg mice." (PMID 31366073, 2019). "Similarly, transplantation of salivary microbiota from periodontitis patients into APP/PS1 mice aggravated amyloid accumulation, neuroinflammation, and cognitive impairment, concomitant with gut dysbiosis, systemic inflammation, and intestinal barrier dysfunction." (PMID 41471945, 2025). "Therefore, cathepsin B, known as an amyloid precursor protein (APP) secretase, may play a critical role in the periodontitis-exacerbated AD and could be a therapeutic target." (PMID 31366073, 2019).
periodontitis (continued). "In this study, we induced experimental periodontitis by P. gingivalis infection in the oral cavity of amyloid precursor protein (APP) transgenic mice and examined the effect of periodontitis on pathophysiology of AD in those mice." (PMID 29134111, 2017). "In APP/PS1 transgenic mice, experimental periodontitis was shown to exacerbate Alzheimer-like pathology by aggravating cognitive deficits, increasing Aβ deposition, enhancing microglial activation, and disrupting both gut microbial balance and intestinal/brain barrier integrity." (PMID 41471945, 2025). "Unlike the mouse model of periodontitis, the APP/PS1 mouse models in our study were never subjected to inoculation with P. gingivalis or molar ligation to induce periodontal bone loss and thus, the outcome cannot be explained by microbial infection." (PMID 37370108, 2023). "Upregulation of APP and its homologs, as well as BACE1 and PS could be found in the present study, indicating that ligature-induced periodontitis could modulate APP processing through enhanced β- and γ-site secretase activity." (PMID 33757547, 2021).
prostate carcinoma (15 papers, 2013 to 2025). A carcinoma that arises from epithelial cells of the prostate gland. "While the role of androgens in cancer, particularly prostate cancer, has been extensively studied, and APP has also been implicated in several androgen-related cancers, the potential interaction between androgens and APP processing pathways is less clear." (PMID 41614805, 2025). "Furthermore, this same study revealed that the copper-binding region of the APP 770 splice variant (in conjunction with tyrosine residues in the APP intracellular domain) reduces copper-mediated inhibition of prostate cancer cell growth." (PMID 26840089, 2016). "Studies have found a relationship between APP and androgen-responsive genes in prostate cancer, implicating APP in malignancy." (PMID 39123408, 2024). "Research has shown that APP affects prostate cancer cell proliferation and migration, with higher APP levels associated with increased migratory activity and the expression of genes linked to metastasis." (PMID 39123408, 2024). "In human PC3 prostate cancer cell line, a correlation between PrPC and the amyloid precursor protein (APP) and its proteolytic fragments (Aβ peptides) has been reported." (PMID 37452879, 2023). "Recently, it was shown that the presence of copper increases the expression of APP in prostate cancer cells." (PMID 26840089, 2016). "The importance of APP in prostate cancer was further validated by an in vivo animal model in which knock-down of APP repressed tumor growth." (PMID 26840089, 2016). "We have previously shown that APP is a primary androgen-responsive gene that promotes the growth of prostate cancer cells." (PMID 23662100, 2013). "So, this may suggest that VD attenuates prostate cancer through androgen-dependent inhibition and cancer cell migration via APP." (PMID 39940287, 2025). "Moreover, APP mediates amyloid β peptide interaction in basal prostate cancer and mesenchymal colon cancer." (PMID 38962272, 2024). "Studies have shown APP regulates the proliferation and migration of prostate cancer cells." (PMID 34066808, 2021). "APP promotes proliferation of breast and prostate cancer cells." (PMID 29587359, 2018). "The APP proliferative effect in prostate cancer may be due to modulation of metalloproteinase genes." (PMID 29587359, 2018). "In addition, APP has been demonstrated to be involved in the migration and proliferation of prostate cancer cells via mechanisms involving metalloproteinases and epithelial-to-mesenchymal transition-related pathways." (PMID 26840089, 2016). "In conclusion, this review highlights the potential role of androgen regulation in APP and its processing in cancer, suggesting that APP and α-secretase enzymes may be modulated by androgens and could contribute to disease progression in breast and prostate cancers." (PMID 41614805, 2025). "They indicated that high APP protein levels correlate with an aggressive cancer stage, and they observed strong nuclear staining for ADAM10 in prostate cancer tissues compared to benign prostate hyperplasia." (PMID 41614805, 2025). "APP protein and APLP2 mRNA are overexpressed in many tumors, including cancers of the prostate, breast, colon, thyroid, lung, nasopharynx, and gastrointestinal tract." (PMID 35875068, 2022). "APP and/or APLP2 have been described as having notable functions in many cancers, such as cancers of the prostate, breast, colon, thyroid, lung, nasopharynx, and gastrointestinal tract (for a more complete list)." (PMID 26840089, 2016). "Importantly, such growth factors play important roles in the growth and survival of cancer cells at all stages of progression and are strongly associated with aggressive prostate cancer, suggesting that the relevance of APP may not be limited to androgen-responsive tumours." (PMID 41614805, 2025).
prostate carcinoma (continued). "We have previously reported that APP contributes to androgen-dependent proliferation of prostate cancer cells and that the rate of cancer-specific survival for patients with APP-positive tumors was lower than that for patients with APP-negative tumors." (PMID 23662100, 2013). "Also, immunohistology revealed a lack of APP in normal human prostate cells, while in tumor samples from a group of prostate cancer patients with a 50% survival rate there was intense cytoplasmic staining of APP." (PMID 26840089, 2016).
Hypercholesterolemia (14 papers, 2008 to 2025). An increased concentration of cholesterol in the blood. "Previous studies have shown that hypercholesterolemia led to APP processing in low-density lipoprotein receptor-deficient mice and in Aβ-injected ApoE−/− mice with an HFD." (PMID 27809235, 2016). "A number of authors have analysed the effect of hypercholesterolaemia in animals in terms of Aβ modulation, reporting it linked to the appearance of Aβ deposits in the brains of rabbits and the acceleration of cerebral Aβ deposition in APP-transgenic mice." (PMID 21829488, 2011). "Various animal studies suggest that hypercholesterolemia increases Aβ by affecting APP processing in vivo." (PMID 35464321, 2022). "Amyloidogenic processing of APP and β-amyloid production are also induced by stress signalling from metals, oxidative stress, excitotoxicity, neuroinflammation, or hypercholesterolaemia." (PMID 28187176, 2017). "Increased APP processing in response to hypercholesterolemia was also observed in the transgenic mice modeling AD on a high-cholesterol diet." (PMID 27809235, 2016). "Accordingly, the APP 110 kDa isoform was unchanged in the hypercholesterolemia and APP_SweDI mouse models." (PMID 25947203, 2015). "In APP transgenic mice, hypercholesterolemia correlates with increased Aβ levels and more severe amyloid plaque load." (PMID 22482072, 2012). "The results suggest recruitment of different focus genes that are related to similar ‘node molecules’, as in the following example: the network in the MCA with largest number of up-regulated focus genes affected by hypercholesterolemia showed many molecules related to APP." (PMID 23874591, 2013). "Although Aβ and APP levels were not affected in the early stages of hypercholesterolemia, the levels of presenilin 1 (PS1) that initiates Aβ production were increased." (PMID 35464321, 2022). "While recently platelet activation and thrombus formation in APP23 mice was investigated, to the best of our knowledge platelet APP, sAPPβ and serotonin have not been studied in hypercholesterolemia and the two AD (APP_SweDI and 3xTg) mouse models." (PMID 25947203, 2015). "Hypercholesterolemia did not significantly trigger platelet changes in AD mouse models, supporting the hypothesis that the observed changes are AD-specific, while a cholesterol diet alone does not alter platelet serotonin levels, APP expression or the secretion of APPβ." (PMID 25947203, 2015). "Moreover, some authors report that plasma cholesterol levels are not significantly altered in classic murine AD models such as Tg-CRND8, APP/PS1 or Tg-SwDI/B, suggesting that these transgenic mice do not replicate the hypercholesterolaemia observed in humans." (PMID 21829488, 2011).
Parkinson's (14 papers, 2013 to 2025). "Indeed, several rare variants of APP predispose individuals to PD, and several studies of familial AD indicate APP mutations are associated with Parkinsonism and LB formation." (PMID 36674772, 2023).
Seizure (14 papers, 2011 to 2026). A seizure is an intermittent abnormality of nervous system physiology characterized by a transient occurrence of signs and/or symptoms due to abnormal excessive or synchronous neuronal activity in the brain. "APP mutations have also been linked with epileptic seizures, for example, T714I, T714A, and V7171G mutations." (PMID 33741601, 2021). "We present a case of a 68-year-old female who presented with epileptic seizures, neuropsychiatric symptoms and progressive memory decline and was found to carry a novel APP variant, c.2062T>G pLeu688Val." (PMID 34830236, 2021). "Seizure occurrence is linked to the abundance of APP and its cleavage fragments, thus changes to mortality may result from alterations in these proteins." (PMID 33707583, 2021). "Seizure susceptibility in 3xTg-AD mice was attenuated either by passive immunization with anti-human APP/Aβ antibody (6E10) or by blockade of metabotropic glutamate receptor 5 (mGluR5) with the selective antagonist, 2-methyl-6-(phenylethynyl)pyridine hydrochloride (MPEP)." (PMID 28392767, 2017). "Seizures and epileptiform discharges have been observed in several strains of AD mice, including J20 and APP/PS1 transgenic models." (PMID 25945128, 2015). "Seizures are frequently observed in APP/PS1 mice at 3 and 4.5 months of age and correlated with mortality that peaks at 3 to 4 months of age." (PMID 22029666, 2011). "Seizures in AD have been shown to occur more often with early-onset disease, particularly when there is a familial presenilin I (PS1) mutation or abnormal expression of amyloid precursor protein (APP)." (PMID 41981995, 2026). "Seizure risk is higher in patients with autosomal dominant AD: a seizure frequency of 47.7%, after mean follow up of 8.4 years was found in AD patients harbouring a pathogenic PSEN1, PSEN2, APP mutation or a duplication of APP." (PMID 38263073, 2024). "Seizures are also common in patients who carry extra copies of APP." (PMID 33741601, 2021). "Seizures are a common feature of EOAD yet no patient for APP missense mutation has been reported." (PMID 30090657, 2018).
astrocytoma (13 papers, 2017 to 2026). "Chlamydia pneumoniae infection of human astrocytoma cells promoted the transcriptional upregulation of numerous genes implicated in host neuroinflammation, lipid homeostasis, microtubule function, and APP processing." (PMID 30786875, 2019). "Grade II-III astrocytomas showed enrichment of pathways related to amyloid precursor protein (APP) processing and amyloid-β clearance, whereas oligodendrogliomas were enriched in lipid transport and negative regulation of amyloid formation." (PMID 42200815, 2026). "Increased APP biosynthesis and amyloid-β transcytosis pathways are associated with poorer survival specifically in grade II-III astrocytoma, suggesting a potential role for amyloid metabolism in tumor progression." (PMID 42200815, 2026). "Analysis showed dose- and time-dependent effects on toxicological endpoints in astrocytoma cells, where higher doses gave reduced viability, changes in expression of apoptotic proteins, reduced expression of APP, and increased intercellular communication." (PMID 30744184, 2019). "Human astrocytoma infected with Cp led to the activation of the pro-amyloidogenic pathway by enhancing APP processing, increased the activity of β-secretase and γ-secretase, and reduced α-secretase, which eventually increased Aβ production by cleaving APP." (PMID 38770241, 2024). "Furthermore, astrocytoma cell lines and normal human astrocytes have increased expression of APP when exposed to TGFβ." (PMID 29237809, 2017). "For example, interleukin-1β has been shown to upregulate APP in human astrocytes and the U373MG human astrocytoma cell line." (PMID 37513235, 2023). "Supporting this, IL-1β has been shown to upregulate APP in human astrocytes and the U373MG human astrocytoma cell line." (PMID 29237809, 2017). "Survival analyses revealed that higher activity of the positive regulation of APP biosynthetic process and amyloid-β clearance by transcytosis was significantly associated with worse overall survival in grade II-III astrocytoma, but not in oligodendroglioma." (PMID 42200815, 2026). "For example, in human 1321N1 astrocytoma cells, the activation of P2Y2R enhanced the release of sAPP alpha, the non-amyloidogenic product of APP with neuroprotective properties, deriving from the alpha-secretase activity." (PMID 35955821, 2022).